MGMT (O-6-methylguanine-DNA methyltransferase)
Diseases named in the same sentence as MGMT in open-access papers (continued):
Sharing a sentence is not in itself a finding about the gene and the disease.
brain diseases (1 paper, 2021). "They underscore the finding that healthy brain tissue is apparently never hypermethylated and that MGMT promoter methylation is only associated with severe brain diseases." (PMID 33917711, 2021). "However, MGMT promoter methylation levels have not yet been investigated in non-neoplastic brain diseases." (PMID 33917711, 2021).
colon polyps (1 paper, 2004). "Examples include, ras-effector nore1A (RASSF1A), stratifin (14-3-3σ), p15 and p16, O6-methylguanine-DNA methyltransferase (MGMT), mismatch repair gene (hMLH1) and hyperplastic colon polyps gene (HPP1)." (PMID 15301688, 2004).
nervous system tumor (1 paper, 2015). "Four nervous system tumor cell lines were used to analyze the modulation of MGMT expression and MGMT promoter methylation by TMZ treatment." (PMID 26447477, 2015). "As such, we used nervous system tumor cell lines exposed to TMZ treatment to analyze the relevance of MGMT, the MMR system, and the ABC transporter in the TMZ resistance phenomenon." (PMID 26447477, 2015).
MGMT also shares sentences with these, for which no sentence is quoted: colon (5 papers); esophageal cancer (5); mental retardation (5); diffuse astrocytoma (4); endometrial cancer (4); head and neck squamous cell carcinoma (4); salivary gland carcinoma (4); Alzheimer disease (3); Cognitive impairment (3); colorectal adenoma (3); gastroenteropancreatic neuroendocrine tumours (3); mental retardation X-linked syndrome (3); oligoastrocytoma (3); oral cavity cancer (3); oral lichen planus (3); Wilms tumor (3); acute leukemia (2); acute lymphoblastic leukaemia (2); Anxiety (2); B-cell lymphoma (2); Cirrhosis (2); clear cell renal cell carcinomas (2); colorectal polyps (2); depression (2); Ewing sarcoma (2); hypopharyngeal cancer (2); leukoplakia (2); liposarcoma (2); malignant peripheral nerve sheath tumor (2); metastasis (2).
A further 104 diseases each share a sentence with MGMT in 2 papers or fewer.